GRB2 (growth factor receptor bound protein 2)
Description:
Non-enzymatic adapter protein that plays a pivotal role in precisely regulated signaling cascades from cell surface receptors to cellular responses, including signaling transduction and gene expression. Thus, participates in many biological processes including regulation of innate and adaptive immunity, autophagy, DNA repair or necroptosis. Controls signaling complexes at the T-cell antigen receptor to facilitate the activation, differentiation, and function of T-cells. Mechanistically, engagement of the TCR leads to phosphorylation of the adapter protein LAT, which serves as docking site for GRB2. In turn, GRB2 establishes a a connection with SOS1 that acts as a guanine nucleotide exchange factor and serves as a critical regulator of KRAS/RAF1 leading to MAPKs translocation to the nucleus and activation. Functions also a role in B-cell activation by amplifying Ca(2+) mobilization and activation of the ERK MAP kinase pathway upon recruitment to the phosphorylated B-cell antigen receptor (BCR). Plays a role in switching between autophagy and programmed necrosis upstream of EGFR by interacting with components of necrosomes including RIPK1 and with autophagy regulators SQSTM1 and BECN1. Regulates miRNA biogenesis by forming a functional ternary complex with AGO2 and DICER1. Functions in the replication stress response by protecting DNA at stalled replication forks from MRE11-mediated degradation. Mechanistically, inhibits RAD51 ATPase activity to stabilize RAD51 on stalled replication forks. Additionally, directly recruits and later releases MRE11 at DNA damage sites during the homology-directed repair (HDR) process. [Isoform 2]: Does not bind to phosphorylated epidermal growth factor receptor (EGFR) but inhibits EGF-induced transactivation of a RAS-responsive element. Acts as a dominant negative protein over GRB2 and by suppressing proliferative signals, may trigger active programmed cell death. Mechanistically, inhibits RAS-ERK signaling and downstream cell proliferation by competing with GRB2 for SOS1 binding and thus by regulating SOS1 membrane recruitment.
Synonyms: ASH; NCKAP2; EGFRBP-GRB2; Grb3-3; MST084; MSTP084
Tractability: Small molecule: a structure with a bound ligand is known; a high-quality ligand is known; it has a high-quality binding pocket. Antibody: its Gene Ontology location is reachable by antibodies, with high confidence. PROTAC: UniProt records ubiquitination sites on it; ubiquitination databases record sites on it; its protein half-life has been measured; a small molecule that binds it is known.
Target class: Other cytosolic protein
Gene: Protein-coding gene on chromosome 17 (75,318,076 to 75,405,709, reverse strand). Ensembl gene ENSG00000177885.
Subcellular location: Nucleus; Cytoplasm; Endosome; Golgi apparatus
Subcellular location (Human Protein Atlas): Cytosol; Centrosome
Pathways (Reactome):
Signal Transduction: Activated NTRK2 signals through FRS2 and FRS3; Activated NTRK2 signals through PI3K; Activated NTRK2 signals through RAS; Activated NTRK3 signals through RAS; Downstream signal transduction; EGFR Transactivation by Gastrin; EGFR downregulation; Erythropoietin activates RAS; FRS-mediated FGFR1 signaling; FRS-mediated FGFR2 signaling; FRS-mediated FGFR3 signaling; FRS-mediated FGFR4 signaling; GAB1 signalosome; GRB2 events in EGFR signaling; GRB2 events in ERBB2 signaling; GRB2:SOS provides linkage to MAPK signaling for Integrins; Insulin receptor signalling cascade; MET activates PI3K/AKT signaling; MET activates PTPN11; MET activates RAP1 and RAC1; MET activates RAS signaling; MET receptor recycling; Negative regulation of FGFR1 signaling; Negative regulation of FGFR2 signaling; Negative regulation of FGFR3 signaling; Negative regulation of FGFR4 signaling; Negative regulation of MET activity; PI-3K cascade:FGFR1; PI-3K cascade:FGFR2; PI-3K cascade:FGFR3; PI-3K cascade:FGFR4; PI3K Cascade; PI3K events in ERBB2 signaling; PI5P, PP2A and IER3 Regulate PI3K/AKT Signaling; PIP3 activates AKT signaling; RAF/MAP kinase cascade; RHO GTPases Activate WASPs and WAVEs; RHOU GTPase cycle; Regulation of KIT signaling; SHC-mediated cascade:FGFR1
and 57 more pathways
Gene Ontology:
Molecular function: ephrin receptor binding; epidermal growth factor receptor binding; guanyl-nucleotide exchange factor adaptor activity; identical protein binding; insulin receptor substrate binding; neurotrophin TRKA receptor binding; phosphotyrosine residue binding; protein binding; protein kinase binding; protein-macromolecule adaptor activity; RNA binding; SH3 domain binding; protein domain specific binding; protein phosphatase binding; transmembrane receptor protein tyrosine kinase adaptor activity
Biological process: actin cytoskeleton organization; cellular response to ionizing radiation; epidermal growth factor receptor signaling pathway; insulin receptor signaling pathway; natural killer cell mediated cytotoxicity; negative regulation of natural killer cell mediated cytotoxicity; positive regulation of reactive oxygen species metabolic process; receptor internalization; signal transduction in response to DNA damage; T cell activation; positive regulation of Rac protein signal transduction; Ras protein signal transduction; regulation of MAPK cascade; signal transduction; B cell receptor signaling pathway; insulin-like growth factor receptor signaling pathway; myelination; Schwann cell development
Cellular component: COP9 signalosome; cytoplasm; cytosol; endosome; extracellular exosome; Grb2-EGFR complex; nucleus; Golgi apparatus; nucleoplasm; plasma membrane; cell cortex; cell-cell junction; membrane; vesicle membrane
Genetic constraint (gnomAD): Loss-of-function variants: 1 observed, 21.99 expected, observed/expected ratio (o/e) 0.0455, 90% interval 0.015 to 0.22. The upper end of that interval is the gene's LOEUF score, 0.22, which puts it in group 1 of 6, group 1 being the genes least tolerant of losing a copy. Missense variants: 84 observed, 253.33 expected, observed/expected ratio (o/e) 0.33, 90% interval 0.28 to 0.4. Synonymous variants: 81 observed, 93.62 expected, observed/expected ratio (o/e) 0.87, 90% interval 0.72 to 1.04.
Homologues: Orthologues: chimpanzee GRB2 (100% identical), dog GRB2 (100% identical), guinea pig GRB2 (100% identical), macaque GRB2 (100% identical), pig GRB2 (100% identical), rat Grb2 (100% identical), mouse Grb2 (99% identical), tropical clawed frog grb2 (97% identical), zebrafish grb2a (94% identical), rabbit GRB2 (89% identical), Drosophila melanogaster drk (64% identical), Caenorhabditis elegans sem-5 (58% identical). Paralogues in human: GRAP (59% identical), GRAP2 (52% identical), GRAPL (31% identical), NCK1 (29% identical), NCK2 (28% identical), SH2D5 (23% identical), SLA (23% identical), SLA2 (22% identical), DAPP1 (21% identical).
Diseases named in the same sentence as GRB2 in open-access papers:
GRB2 is named in the same sentence as 170 diseases in open-access papers, as found by Europe PMC text mining. Sharing a sentence is not in itself a finding about the gene and the disease. The quoted sentences say what the papers report.
breast carcinoma (61 papers, 2010 to 2025). "We found that GRB2 was highly expressed in breast cancer tissues and was linked to a poor outcome for patients by using the TCGA, HPA, and UALCAN databases." (PMID 40384436, 2025). "Grb2 is an adaptor protein that can associate either directly or indirectly with ErbB2, an oncogene associated with poor survival in breast cancer patients." (PMID 37242677, 2023). "Downregulation of DAB2 significantly increases the association of SOS with Grb2 in M1 breast cancer cells, enhancing ERK phosphorylation and activating TGFβ signaling mediated EMT." (PMID 37815603, 2023). "Upon epidermal growth factor (EGF) stimulation, p66Shc and Grb-2 potentiate cell proliferation, invasion, and migration in breast cancer cells by associating with small GTPases ARF-1 and ARF-6; and coordinating their activation." (PMID 35273919, 2022). "The overexpression of GRB2 has been demonstrated to be significantly associated with the occurrence and poor prognosis of breast cancer." (PMID 32461838, 2020). "We performed GRB2 affinity purification combined with mass spectrometry analysis of associated proteins in a HER2+ breast cancer model to delineate GRB2-nucleated protein interaction networks." (PMID 28912526, 2017). "We combined GRB2 affinity purification (AP) with mass spectrometry (MS) identification of associated proteins in HER2+ breast cancer cells to delineate GRB2-nucleated protein interaction networks." (PMID 28912526, 2017). "In conclusion, we want to investigate the potential involvement of GRB2 in HER2‐overexpression breast cancer and offer a novel therapeutic approach." (PMID 40384436, 2025). "GRB2 co-immunoprecipitated with BECN1 in several breast cancer cell lines and regulates autophagy through a mechanism involving the modulation of the class III PI3Kinase VPS34 activity." (PMID 38182563, 2024). "In the samples of breast cancer patients, GRB2 nuclear expression was higher than that of normal tissues." (PMID 38540680, 2024). "Liposomal Grb2 ASO treatment decreased cell growth in EGFR-overexpressing breast cancer cells, and liposomal Bcl-2 ASO treatment resulted in a significant induction of apoptosis in 11 of 19 patient samples." (PMID 37242677, 2023). "hsa-miR-27b-3p directly targets HSP90AA1 and Fzd7 in NSCLC, ROR1 in gastric cancer, and CBLB/GRB2 in breast cancer to suppresses cell proliferation, migration, invasion, and expression of MET." (PMID 34603447, 2021). "Plenty of miRNA-mRNA axes, such as miR-34a-Notch1 axis, miR-125b-Sema4c axis, miR-181-Bcl-2 axis, and miR-27b/CBLB/GRB2 axis, were reported that regulated taxanes-resistance in breast cancer." (PMID 32974144, 2020). "Research shows that many types of malignancies, such as breast cancer, are characterized by upregulated GRB2-MAPK pathway, especially since GRB2 is coded in a chromosome region duplicated in many types of neoplasms." (PMID 31719636, 2019). "GRB2 has been found to be overexpressed in many tumours, such as breast cancer, along with EGF receptor and components of the RAS/MAPK signalling pathway." (PMID 30087284, 2018). "We further showed that the mechanism by which BST-2 dimerization promotes breast cancer involves a previously unreported BST-2/GRB2/ERK/BIM/Cas3 pathway." (PMID 29523843, 2018). "Above results definitely indicated miR-27b negatively regulated CBLB and GRB2 by direct binding in breast cancer cells." (PMID 29416005, 2018). "Studies on breast cancers have revealed that formation of GRB2: TβRII complex is essential for mammary cancer growth mediated by TGF-β." (PMID 30087284, 2018). "The loss of BST-2 dimerization-mediated cell to cell/ECM interaction inhibits cancer cell clustering, induces anoikis in breast cancer cells through BST-2/GRB2/ERK/BIM/Cas3 pathway, and inhibits tumor growth and metastasis." (PMID 29523843, 2018).
breast carcinoma (continued). "Expression of GRB2 has been reported to be elevated in human breast cancer biopsies, and the role of GRB2 in tumour progression has been studied widely in breast tumour." (PMID 30087284, 2018). "To examine the requirement for PTPN11 in complex formation in HER2+ breast cancer cells, we analyzed GRB2 and MPZL1 localization in cells depleted of PTPN11." (PMID 28912526, 2017). "Recently, studies have shown that GRB2 is highly expressed in bladder cancer, breast cancer and esophageal cancer and that GRB2 is closely related to poor prognosis." (PMID 29296185, 2017). "In our studies, we identified BST-2/GRB2/ERK/BIM/Cas3 as an important pathway in anoikis evasion by breast cancer cells." (PMID 28300825, 2017). "In summary, we found that in ErbB2-overexpressing breast cancer cells the ErbB2/Grb2 interaction leads to the direct activation of RAS which, in turn, mediates via interaction with p110α the p-AKT rebound in response to an incomplete blockade of ErbB2." (PMID 27255951, 2016). "We have recently shown that lemur receptor tyrosine kinase 3 (LMTK3) promotes invasion in breast cancer through GRB2-mediated induction of integrin family members, supporting our data presented here." (PMID 26089344, 2015). "Phosphorylation of Y160 on Grb2 is readily detectable in the malignant forms of human prostate, colon and breast cancers." (PMID 26103942, 2015). "The Giα proteins associated with RTKs, Gab1, FRS2 and Shp2 in breast cancer cells and their ablation impaired Gab1’s interactions with Shp2 in response to EGF and IGF-1, or with FRS2 and Grb2 in response to bFGF." (PMID 24521094, 2014). "Silencing GRB2 inhibited cell proliferation and invasion; LMTK3 kinase facilitated the invasion of breast cancer by inducing integrin β1 through GRB2‐mediated paths; and MiR‐27b directly targeted CBLB and GRB2 to deactivate the MAPK pathways, which improved the response to paclitaxel." (PMID 40384436, 2025). "Above, these AS events may be regulated by GRB2 to promote the progression of HER2‐overexpression breast cancer." (PMID 40384436, 2025). "In summary, GRB2 is connected with the advancement of HER2‐overexpression breast cancer." (PMID 40384436, 2025). "We hypothesize that GRB2 may lead to the development of breast cancer by increasing the expression of these genes." (PMID 40384436, 2025). "Integration analysis of RNA‐seq and fRIP‐seq data identified 63 genes that overlap, indicating that GRB2 may have an essential function in breast cancer." (PMID 40384436, 2025). "We report that TME lactate triggers the assembly of the lactate receptor hydroxycarboxylic acid receptor 1 (HCAR1)-associated protein complex, which includes GRB2, SOS1, KRAS, GAB1, and PI3K, for the activation of both the RAS and the PI3K oncogenic signaling pathways in breast cancer (BCa) cells." (PMID 39199589, 2024). "In addition, it has previously been shown that SNTA1/Grb2/p66Shc signaling complex enhances Rac1 activation that in turn augments metastatic characteristics of breast cancer cells." (PMID 35273919, 2022). "For example, in breast cancer, Grb2 links with SHP1 to proceed tumor progression." (PMID 34305583, 2021). "THSWD treatment of breast cancer may be related to targeting Ras, FoxO, PI3K-Akt, and other signal pathways associated with the core targets HRAS, MAPK1, AKT1, GRB2, and MAPK14." (PMID 34513708, 2021). "The GRB2 is overexpressed in breast cancers, and is a key molecule in intracellular signal transduction, which can directly interact with RTKs, such as epidermal growth factor receptor (EGFR) to activate several downstream oncogenic signaling pathways, including PI3K-Akt and RAS signaling." (PMID 32350346, 2020). "miR-411-5p was observed to suppress breast cancer by downregulating GRB2 and Ras expression." (PMID 29579063, 2018). "In an invasive breast cancer cell line, GRB2 was found to regulate GTPases activation, and may also trigger ATF4 and ATF6." (PMID 28767067, 2017).
breast carcinoma (continued). "We have used AP-MS to map a GRB2-centric protein interaction network in HER2+ breast cancer cells." (PMID 28912526, 2017). "The central role of GRB2 in HER2 signalling led us to hypothesize that the analysis of modifications within the GRB2 protein interaction network in HER2+ breast cancer cells would lead to the identification of key components required for downstream signalling." (PMID 28912526, 2017). "There is a significant association between the protein tyrosine phosphatase PTPN6 (SHP-1) and GRB2 expression, which may amplify tyrosine kinase signaling in human breast cancer." (PMID 28938536, 2017). "Studies have shown that Grb2 overexpressed in breast cancer tissue." (PMID 27699085, 2016). "Using a novel phosphopeptide microarray technology, we have mapped endogenous tyrosine-phosphoproteome interaction networks in breast cancer cells mediated by signaling adaptor protein GRB2, which transduces cellular responses downstream of several RTKs through the Ras-ERK signaling cascade." (PMID 23826330, 2013). "We speculate that GRB2 may aid breast cancer progress by decreasing the expression of these genes." (PMID 40384436, 2025). "We hypothesize that GRB2 may affect AS, which may promote breast cancer." (PMID 40384436, 2025). "Previous studies suggested that GRB2 might be involved in breast tumorigenesis, since mice overexpressing Grb2 enhanced mammary tumorigenesis, while Grb2+/- mice delayed the onset of mammary tumors." (PMID 38182563, 2024). "Furthermore, both GRB2 and MEK5/ERK5 are commonly overexpressed in breast cancer and associated with poor overall survival, and targeting of these proteins/pathways is shown to suppress breast cancer progression." (PMID 31921382, 2019). "However, in breast cancer, the functions of GRB2 underlying miR-27b-mediated drug sensitivity were not clear." (PMID 29416005, 2018). "Our data suggest that the results are robust in different NSCLC datasets and the key target genes identified (ITGA2B, FLNA, GRB2, FCGR2A, and APP, etc.)seem to also be strongly expressed in the breast cancer and pancreatic cancer datasets we analyzed." (PMID 41226816, 2025). "Although some studies have found a connection between GRB2 and HER2‐overexpression breast cancer, highlighting the potential of GRB2 as a novel biomarker that stimulates tumor growth, limited data were available to elaborate on their interaction mechanisms." (PMID 40384436, 2025). "Lopez-Berestein and his colleagues worked with liposomal ASOs targeting Grb2 (BP1001, Prexigebersen) and Bcl-2 oncogenes for breast cancer and leukemia cells, respectively." (PMID 39272802, 2024). "In breast carcinoma cells, the Sema4D activation of Plexin B1 leads to its tyrosine phosphorylation by MET, creating a docking site for the SH2 domain of Grb2." (PMID 39769452, 2024). "Axon guidance signalling proteins Paxillin (PXN) and Reticulon4 (RTN4) showed increased abundance, while GIT1, GRB2 and SHRANK2 showed decreased abundance in breast cancer cells after co-culture." (PMID 39232464, 2024). "Meanwhile, upregulation of GRB2 (log FC = 3.9, p = 0.016) and ERBB2 (log FC = 5.6, p = 0.026) expression was detected in mammary carcinoma tissue with grade III (n = 3)." (PMID 34679042, 2021). "In this study, we first time confirmed GRB2, as direct target of miR-27b, significantly suppressed by miR-27b thereby downregulating the activities of MAPK/Erk signaling pathways in breast cancers." (PMID 29416005, 2018). "All these results suggested that miR-27b attenuated breast cancer cell resistance to PTX by repressing CBLB and GRB2." (PMID 29416005, 2018). "The MTT assays showed downregulation of CBLB or GRB2 expression significantly inhibited cell proliferation, and increased cell sensitivity to PTX in breast cancer cells." (PMID 29416005, 2018).